OTX2 (orthodenticle homeobox 2)
Description:
Transcription factor probably involved in the development of the brain and the sense organs. Can bind to the bicoid/BCD target sequence (BTS): 5'-TCTAATCCC-3'.
Synonyms: CPHD6; MCOPS5
Tractability: No criterion of Open Targets' tractability assessment is met for any kind of drug.
Gene: Protein-coding gene on chromosome 14 (56,799,905 to 56,816,693, reverse strand). Ensembl gene ENSG00000165588.
Subcellular location: Nucleus
Subcellular location (Human Protein Atlas): Nucleoplasm; Vesicles
Pathways (Reactome):
Developmental Biology: Formation of the anterior neural plate; Formation of the posterior neural plate
Gene Ontology:
Molecular function: DNA-binding transcription activator activity, RNA polymerase II-specific; protein binding; RNA polymerase II cis-regulatory region sequence-specific DNA binding; sequence-specific double-stranded DNA binding; DNA-binding transcription factor activity, RNA polymerase II-specific; eukaryotic initiation factor 4E binding; DNA binding; DNA-binding transcription factor activity
Biological process: axon guidance; dopaminergic neuron differentiation; positive regulation of transcription by RNA polymerase II; protein-containing complex assembly; forebrain development; midbrain development; positive regulation of DNA-templated transcription; positive regulation of embryonic development; positive regulation of gastrulation; primitive streak formation; regulation of fibroblast growth factor receptor signaling pathway; regulation of smoothened signaling pathway; regulation of transcription by RNA polymerase II; regulation of DNA-templated transcription
Cellular component: growth cone; nucleoplasm; nucleus; protein-containing complex; chromatin
Genetic constraint (gnomAD): Loss-of-function variants: 4 observed, 28.25 expected, observed/expected ratio (o/e) 0.14, 90% interval 0.069 to 0.32. The upper end of that interval is the gene's LOEUF score, 0.32, which puts it in group 1 of 6, group 1 being the genes least tolerant of losing a copy. Missense variants: 290 observed, 378.51 expected, observed/expected ratio (o/e) 0.77, 90% interval 0.69 to 0.84. Synonymous variants: 133 observed, 148.41 expected, observed/expected ratio (o/e) 0.9, 90% interval 0.78 to 1.03.
Homologues: Orthologues: chimpanzee OTX2 (100% identical), mouse Otx2 (99% identical), pig OTX2 (99% identical), macaque OTX2 (97% identical), rat Otx2 (97% identical), guinea pig OTX2 (97% identical), dog OTX2 (96% identical), rabbit OTX2 (96% identical), tropical clawed frog otx2 (93% identical), zebrafish otx2b (91% identical). Paralogues in human: OTX1 (67% identical), CRX (54% identical), PAX7 (27% identical), PAX3 (26% identical), ARX (26% identical), PITX1 (25% identical), PITX2 (25% identical), ARGFX (24% identical), OTP (24% identical), RAX (24% identical), PAX6 (23% identical), UNCX (23% identical), and 38 more.
Diseases named in the same sentence as OTX2 in open-access papers:
OTX2 is named in the same sentence as 121 diseases in open-access papers, as found by Europe PMC text mining. Sharing a sentence is not in itself a finding about the gene and the disease. The quoted sentences say what the papers report.
medulloblastoma (49 papers, 2008 to 2025). A malignant, invasive embryonal neoplasm arising from the cerebellum. "Our triplet links also include 60 genes known to be recurrently mutated or overexpressed in medulloblastoma, including OTX2, MYCN, the Fanconi anemia proteins FANCA and FANCI, and others." (PMID 41279093, 2025). "OTX2 is also expressed in a large proportion (>66%) of medulloblastomas and is specifically associated with vermian topography and classic, large cell, and anaplastic variants." (PMID 38069286, 2023). "For example, OTX2, an oncogenic orthodenticle homeobox protein that directly activates cell cycle genes and inhibits differentiation in medulloblastomas, is strongly associated with OS in the greyhounds." (PMID 24330828, 2013). "The overexpression of OTX2 was later confirmed to be causal for certain medulloblastomas type." (PMID 31370908, 2019). "While confirming this hypothesis will require the analysis of a large number of cases, we suggest clinicians be aware of the possibility of increased risk for medulloblastoma in HFM cases with OTX2 duplications." (PMID 24816892, 2014). "Dysregulation of Otx2 is a hallmark of the pediatric brain tumor medulloblastoma, yet its functional significance in the establishment of these tumors is unknown." (PMID 22558385, 2012). "Even germline duplications of chromosome 14q22.3 including OTX2 were described rarely in medulloblastomas." (PMID 41291966, 2025). "These include enhancers of regulators of genes that drive glutamatergic neuronal identity (e.g., PAX6, WLS), and known drivers of medulloblastoma (OTX2, MYCN, CBFA2T2)." (PMID 41279093, 2025). "It has been reported in studies that OTX‐2 is overexpressed especially in medulloblastoma, a blastoma‐derived tumor." (PMID 38925618, 2024). "Gene expression in the medulloblastoma was found to be upregulated by OTX2 and MYC binding in close proximity to each other at transcription start sites of genes contributing to the cancer phenotype." (PMID 38925618, 2024). "CDK8 stands out as a top dependency, similar to OTX2, Neurog1, and Neurod1, well-established genes that sustain stemness and drive proliferation in medulloblastoma 34–37." (PMID 39574899, 2024). "Due to its function as a transcription factor, OTX2 activates and downregulates genes that help the aggressive medulloblastoma subtypes develop." (PMID 38925618, 2024). "As a transcription factor, OTX‐2 preferentially activates and represses genes that favor the development of aggressive forms of medulloblastoma." (PMID 38925618, 2024). "OTX2 is a transcription factor and known driver in medulloblastoma (MB), where it is amplified in a subset of tumours and overexpressed in most cases of group 3 and group 4 MB." (PMID 39025928, 2024). "In the case of medulloblastoma, OTX‐2 and MYC were shown to bind tightly to each other in the transcription start sites of genes that contribute to the cancer phenotype." (PMID 38925618, 2024). "An oncogenic role for OTX2 has been demonstrated in the proliferation and progression of medulloblastoma in which OTX2 induces epigenetic modifications restoring a stem cell-like phenotype." (PMID 37301955, 2023). "The novel finding of OTX2 oncogene gain in 42/108 (39%) WNT medulloblastomas was identified using molecular inversion probe (MIP) array technology and was associated with significantly worse progression free survival (PFS) and OS." (PMID 36403175, 2023). "OTX2 overexpression is also found in some cases of medulloblastoma, repressing transcription of differentiation markers." (PMID 37181651, 2023).
medulloblastoma (continued). "This confirms that OTX2 is functionally cooperating with MYC to regulate gene expression in medulloblastoma." (PMID 37016281, 2023). "OTX2 controls the regulatory landscape medulloblastoma through cooperative activity at enhancer elements and contributes to the expression of critical target genes." (PMID 37821907, 2023). "OTX2 can directly activate c-MYC expression in medulloblastoma via cis-regulatory elements in MYC promoter." (PMID 37181651, 2023). "Recently, an ex vivo model of medulloblastoma was developed by overexpression of Otx2/c-MYC in cerebellar organoids which showed a disease-specific DNA methylation signature." (PMID 35978801, 2022). "Complex rearrangement and focal deletions of the DDX31 gene have also been observed in several Group 4 medulloblastomas; these deletions occur concurrently with amplification of the OTX2 locus, a known medulloblastoma oncogene." (PMID 34795224, 2021). "Studies showed that NEK2, OTX2 target gene, was knockdown and pharmacological inhibition decreased medulloblastoma cell viability." (PMID 33101383, 2020). "Orthodenticle homologue 2 (OTX2) amplification was identified in medulloblastomas using digital karyotyping." (PMID 31370908, 2019). "The data presented here urge to tackle these critical questions, as OTX2 appears as an attractive candidate for molecularly targeted therapy in a large fraction of medulloblastomas." (PMID 30100614, 2018). "The dataset, corresponding to this batch, has been obtained from GEO under code GDS4472 titled Transcription factor oncogene OTX2 silencing effect on D425 medulloblastoma cell line: time course." (PMID 30127855, 2018). "Of note, the localization, growth rate and histology of tumours induced in Otx2+ GCPs correspond to bona-fide classical type of Shh medulloblastoma." (PMID 30100614, 2018). "OTX2 is overexpressed in all types of medulloblastomas, except in Shh-dependent type 2 medulloblastomas, although it has GCPs as cell-of-origin." (PMID 30100614, 2018). "OTX2 levels are abnormally increased in Group 3 and 4 medulloblastomas, with >80% of these tumors displaying either recurrent gain or overexpression of this homeobox gene." (PMID 30279357, 2018). "Particularly, in medulloblastoma cells, OTX2 levels are negatively correlated with those of Semaphorin A pathway genes." (PMID 30279357, 2018). "A recent study provided evidence that OTX2 promotes self-renewal and inhibits differentiation of medulloblastoma stem cells and increases tumor-initiating capacity of these cells." (PMID 30279357, 2018). "The oncogenic role of OTX2 in the formation of cerebellar tumours has been supported by functional data, showing that silencing of OTX2 expression in medulloblastoma cell lines reduces their proliferation potential in vitro and their tumorigenic properties." (PMID 30100614, 2018). "It seems contradictory, at first, that Otx2 overexpression is found in all types of medulloblastomas except in Shh type, as the latter is known to originate from GCPs." (PMID 30100614, 2018). "In fact, there have been cases reported of concurrent trilateral retinoblastoma and medulloblastoma in the same patient, which additionally supports the theory about the role of OTX2 as an oncogene in these cancers." (PMID 29124525, 2017). "High expression of OTX2 in medulloblastoma together with c-MYC and MYCN oncogenes, correlates with anaplasticity and unfavorable patient outcome." (PMID 29124525, 2017). "The fact that OTX2 is also known as an oncogenic driver in medulloblastoma, a condition that was diagnosed in the proband of the family during the course of the study." (PMID 29311971, 2017). "WNT medulloblastomas show nuclear accumulation of β-catenin protein in addition to Yap1 immunoreactivity in tumor nuclei and express Otx2." (PMID 27781424, 2016).
medulloblastoma (continued). "Similar to our previous studies on metabolic activity, the strongest effect on overall clonogenic survival was found in the OTX2-expressing D283-Med cell line, supporting recent findings of OTX2 as a medulloblastoma oncogene and possible target for ATRA." (PMID 27317342, 2016). "The identification of a positive feedback loop maintaining OTX2 expression in medulloblastoma suggests that disruption of this loop is a requisite step in the repression of OTX2 during neural development." (PMID 25198066, 2014). "Considering the potential role of retinoids in regulating OTX2 in the eye, these observations led us to investigate the role of the DHS “R” regulatory element in retinoid-induced repression of OTX2 in medulloblastoma." (PMID 25198066, 2014). "Comparison of medulloblastoma regulatory elements with those of the developing brain reveals that these tumors engage a developmental regulatory program to drive OTX2 transcription." (PMID 25198066, 2014). "Known developmental repressors of OTX2 in the hindbrain include Gbx2 and Fgf8; however, these genes are rarely expressed in established medulloblastomas." (PMID 25198066, 2014). "The OTX2 germline duplication in our subjects suggests a potential link to the medulloblastoma of the proband." (PMID 24816892, 2014). "Taking a cue from its developmental regulation, we and others have demonstrated that retinoic acid can repress transcription of OTX2 and inhibit medulloblastoma growth." (PMID 25198066, 2014). "The potential biological link between OTX2 duplications in hemifacial microsomia and medulloblastoma raises the possibility of their comorbidity." (PMID 24816892, 2014). "Given the accumulation of chromatin structure data for a variety of tissue contexts, we then sought to compare the regulatory landscape of OTX2 in medulloblastoma with that of related CNS tissues." (PMID 25198066, 2014). "As validation that autoregulation is not an overexpression artifact, chromatin immunoprecipitation of endogenous OTX2 specifically enriched the DHS 4 fragment in OTX2-expressing medulloblastoma cells." (PMID 25198066, 2014). "To this end, we determined the methylation status of OTX2 by bisulfite sequencing in a cohort of medulloblastomas." (PMID 25198066, 2014). "Our findings suggest a role for OTX2 dosage sensitivity in human craniofacial development and raise the possibility of a shared etiology between a subtype of hemifacial microsomia and medulloblastoma." (PMID 24816892, 2014). "In OTX2-expressing medulloblastoma cells, we found that ectopic OTX2 indeed enhanced the expression of endogenous OTX2." (PMID 25198066, 2014). "To this end, we have also investigated transcriptional regulatory elements mediating retinoid-induced OTX2 repression in medulloblastoma cells." (PMID 25198066, 2014). "This work characterizes for the first time the mechanisms of OTX2 overexpression in medulloblastoma." (PMID 25198066, 2014). "Knockdown of OTX2 with distinct siRNA's completely abolished enhancer activity of DHS 4 in OTX2-expressing medulloblastoma cells." (PMID 25198066, 2014). "This dataset has been obtained from GEO under code GDS4472 titled transcription factor oncogene OTX2 silencing effect on D425 medulloblastoma cell line: time course." (PMID 25143987, 2014). "In established medulloblastomas, Otx2 inhibits differentiation and can contribute to tumor progression." (PMID 22558385, 2012). "In this study, we have determined that the medulloblastoma oncogene Otx2 promotes enhanced migration and persistent proliferation of hindbrain neuronal progenitor cells away from their mitogenic niches." (PMID 22558385, 2012). "Here we have sought to determine the functional consequences of Otx2 overexpression in the mouse hindbrain to characterize its potential role in medulloblastoma tumorigenesis and identify the cell types responsive to this lineage-specific oncogene." (PMID 22558385, 2012).
medulloblastoma (continued). "Otx2-induced ectopia of the cerebellum and brainstem were reminiscent of preneoplastic cells identified in animal models of Shh and Wnt group medulloblastomas, respectively." (PMID 22558385, 2012). "In the present study, we have sought to determine the consequences of ectopic Otx2 expression in the mouse hindbrain to identify the cell types and developmental processes affected by dysregulated Otx2 as is observed in medulloblastoma." (PMID 22558385, 2012). "Despite broad overexpression of Otx2, this oncogene distinctly affected cerebellar GNPs and brainstem neuronal progenitors, both of which are known cell origins of medulloblastoma." (PMID 22558385, 2012). "Of transformed tissues, Otx2 is expressed only in medulloblastoma and retinoblastoma, attesting to its lineage specificity." (PMID 22558385, 2012). "Although OTX2 is an essential gene in medulloblastoma, little is known about the mechanism by which OTX2 regulates the expression of its target genes." (PMID 22016811, 2011). "Expression profiling after induction of ectopic OTX2 or silencing endogenous OTX2 in medulloblastoma cell lines revealed over 2000 genes regulated downstream of OTX2, including many cell cycle and eye developmental genes." (PMID 22016811, 2011). "These high OTX2 levels together with amplification or gain of the OTX2 locus in a subset of the tumors suggest an oncogenic role for OTX2 in medulloblastoma." (PMID 22016811, 2011). "This is in good agreement with our current observation that OTX2 is highly expressed in all medulloblastomas, except for cluster B tumors." (PMID 18769486, 2008). "Early gene expression profiling studies, using serial analysis of gene expression, identified the homeobox gene OTX2 as highly expressed and occasionally amplified in medulloblastoma." (PMID 18769486, 2008). "Another study revealed that OTX2 works synergistically with MYC in oncogenesis in medulloblastoma." (PMID 38925618, 2024). "Various studies have demonstrated that all-trans retinoic acid (ATRA) repressed OTX2 expression and inhibited OTX2-expressing medulloblastoma cell growth, suggesting that medulloblastomas may be amenable to therapy with retinoids." (PMID 38069286, 2023). "In addition to its expression levels, OTX2 is also duplicated in several MB with no WNT or SHH activated pathways, thus leading several studies to elucidate an OTX2 oncogenic role in medulloblastomas." (PMID 38069286, 2023). "In fact, oncogenic properties exerted by OTX2 are associated with MYC, another typically amplified and/or overexpressed gene in medulloblastoma, which is directly induced by OTX2 and frequently colocalizes with OTX2 to promoters of MB and embryonic/neural stem cell specific genes." (PMID 38069286, 2023). "Notably, concurrent trilateral retinoblastoma and medulloblastoma has been reported, and aberrant OTX2 expression is a common characteristic." (PMID 37181651, 2023). "Mutually exclusive mutations in group 4 medulloblastomas could be attributed to the effect of the core binding factor (CBFA) and include CBFA2T2, CBFA2T3, PRDM6, UTX, and OTX2 genes." (PMID 36829544, 2023). "Chromatin accessibility is altered in medulloblastoma, where histone modifications may allow for increased OTX2 expression, and hence a positive feedback loop for OTX2." (PMID 35546872, 2022). "It has been postulated that the cellular context dependent nature of OTX2 expression could attribute to its overexpression in some groups of medulloblastoma." (PMID 35546872, 2022).